ADAM17 (ADAM metallopeptidase domain 17)
Diseases named in the same sentence as ADAM17 in open-access papers (continued):
Sharing a sentence is not in itself a finding about the gene and the disease.
cardiac hypertrophy (17 papers, 2016 to 2025). "Collectively, decreased ADAM17 expression is associated with the protective effect of the PPAR-α activator fenofibrate on pressure overload-induced cardiac hypertrophy." (PMID 30105051, 2018). "In summary, a reduction in ADAM17 expression is associated with the protective action of PPAR-α agonists against pressure overload-induced cardiac hypertrophy." (PMID 30105051, 2018). "There is evidence showing that vascular ADAM17-deficient mice and ADAM17 antibody treated mice have alleviated Ang II-induced cardiac hypertrophy, vascular medial hypertrophy, and perivascular fibrosis via activating EGFR, which is independent of blood pressure regulation." (PMID 37521117, 2023). "Compared with control mice, vascular ADAM17-deficient mice and ADAM17 antibody treated mice show alleviated cardiac hypertrophy, vascular medial hypertrophy, and perivascular fibrosis induced by Ang II via activating EGFR, which is independent of blood pressure regulation." (PMID 37521117, 2023). "ADAM17 has previously been shown to regulates pressure overload-induced myocardial hypertrophy and dysfunction through proteolytic processing of integrin β1." (PMID 37046278, 2023). "Nox4 is a major enzyme that produces ROS, and oxidative stress involving the Nox4/ROS/ADAM17 signalling pathway was inseparable from the pathogenesis of cardiac hypertrophy." (PMID 37528096, 2023). "Considering that Nox4, a gene downstream of BRD4, is a major resource for ROS in the heart and can promote cardiac hypertrophy mediated through the Nox4/ROS/ADAM17 pathway, the change in Nox4 protein and mRNA was analysed first." (PMID 37528096, 2023). "Our previous study indicated that NADPH oxidase 4 (Nox4) promotes angiotensin II (Ang II)‐induced cardiac hypertrophy through the pathway between reactive oxygen species (ROS) and a disintegrin and metalloproteinase‐17 (ADAM17) in primary cardiomyocytes." (PMID 30953402, 2019). "Our previous results showed that ADAM17 siRNA markedly attenuated angiotensin II-induced cardiac hypertrophy in primary cardiomyocytes." (PMID 30105051, 2018). "Our previous results also showed that ADAM17 siRNA inhibited angiotensin II-induced cardiac hypertrophy in primary cardiomyocytes." (PMID 30105051, 2018). "In cultured primary cardiomyocytes, PPAR-α activation inhibited angiotensin II-induced cardiac hypertrophy and decreased ADAM17 protein and mRNA levels." (PMID 30105051, 2018). "In this research, we found that PPAR-α activation by fenofibrate ameliorated pressure overload-induced cardiac hypertrophy and reduced ADAM17 expression in left ventricular tissue in AAC-induced hypertensive rats." (PMID 30105051, 2018). "Systemic ADAM17 knockdown was shown to ameliorate cardiac hypertrophy in angiotensin II-induced hypertensive mice and spontaneously hypertensive rats." (PMID 30105051, 2018). "Abdominal artery constriction- (AAC-) induced hypertensive rats were used to observe the effects of fenofibrate on cardiac hypertrophy and ADAM17 expression." (PMID 30105051, 2018). "In the present study, our findings indicated that fenofibrate alleviated cardiac hypertrophy and reduced ADAM17 expression in hypertrophic cardiomyocytes in vivo and in vitro experiments." (PMID 30105051, 2018). "In conclusion, our indirect evidence indicates that a decrease in ADAM17 expression is related to the beneficial role of PPAR-α activation in pressure overload-induced cardiac hypertrophy." (PMID 30105051, 2018). "Together, these lines of indirect evidence showed that inhibition of ADAM17 modulated the protective action of fenofibrate against angiotensin II-induced cardiac hypertrophy." (PMID 30105051, 2018). "Our previous study indicated that a disintegrin and metalloproteinase-17 (ADAM17) is required for angiotensin II-induced cardiac hypertrophy." (PMID 30105051, 2018).
cardiac hypertrophy (continued). "For example, systemic treatment of ADAM17-targeting siRNA for 30 days effectively stopped the progression of agonist-induced cardiac hypertrophy and fibrosis in adult spontaneously hypertensive rats and mice following Ang-II infusion." (PMID 27803674, 2016). "This further fuels the involvement of ADAM17 in cardiac hypertrophy, as has been shown in both animal and human studies." (PMID 27803674, 2016). "Previous studies have shown that Nox4 promotes cardiac hypertrophy via the ROS/ADAM17 pathway." (PMID 37528096, 2023). "Also, the production of ROS mediated by NADPH oxidase 4 (NOX4) is required to induce ADAM17 expression and following induction of cardiac hypertrophy." (PMID 36310604, 2022). "Available evidence showed that ADAM17 expression was elevated in the myocardium of patients with dilated cardiomyopathy and ADAM17 gene silencing prevented Ang II-induced cardiac hypertrophy and fibrosis in mice." (PMID 36313337, 2022). "However, cardiomyocyte-specific ADAM17 knockdown was reported to aggravate cardiac hypertrophy by reducing integrin β1 cleavage in mice after transverse aortic constriction." (PMID 35909160, 2022). "Although ADAM17 exerts potential regulatory effects in cardiovascular diseases, including cardiac hypertrophy, coronary microvascular dysfunction, and thoracic aortic aneurysm, its precise function in cardiac fibrosis remains unknown." (PMID 34035876, 2021). "Similarly, in vitro experiments showed that fenofibrate significantly attenuated angiotensin II-induced cardiac hypertrophy and diminished ADAM17 mRNA and protein levels in primary cardiomyocytes stimulated with angiotensin II." (PMID 30105051, 2018). "Fatty acid uptake/utilization mismatch in the heart leads to lipid accumulation that is related to initial cardiac hypertrophy; however, it needs to elucidate whether ADAM17 mediates cardiac hypertrophy through lipids accumulation in the heart." (PMID 30105051, 2018). "Therefore, these lines of indirect evidence indicate that a decrease in ADAM17 expression is involved in the protective effect of fenofibrate on pressure overload-induced cardiac hypertrophy." (PMID 30105051, 2018). "This study aimed to determine whether ADAM17 is involved in the protective action of fenofibrate against cardiac hypertrophy." (PMID 30105051, 2018). "Furthermore, ADAM17 silencing prevents Ang II-induced cardiac hypertrophy and fibrosis in mice." (PMID 38799171, 2024). "Indeed, a recent study involving vascular ADAM17-deficient mice implicated VSMC ADAM17 in Ang II-induced cardiac hypertrophy, independent of increased blood pressure." (PMID 36651286, 2023). "Our previous results revealed that ADAM17 siRNA could attenuate cardiac hypertrophy, as indicated by its effects on cell surface area and mRNA levels of hypertrophic genes (ANP and BNP) in primary cardiomyocytes stimulated with 100nM angiotensin II for 24 hours." (PMID 30105051, 2018). "However, further research is needed to elucidate whether and how ADAM17 mediates the protective effects of fenofibrate on cardiac hypertrophy in hypertensive rats overexpressing ADAM17 gene in combination with fenofibrate treatment." (PMID 30105051, 2018). "However, it remains unclear whether ADAM17 participates in the protective effect of fenofibrate against cardiac hypertrophy." (PMID 30105051, 2018). "Therefore, ADAM17 is a crucial factor that mediates pressure overload-induced cardiac hypertrophy." (PMID 30105051, 2018). "Meanwhile, deficiency of TIMP3 has been found capable to suppress Ang II-induced cardiac hypertrophy, but to enhance pressure overload-induced DCM primarily due to increased activity of ADAM17, TNFα and MMPs." (PMID 37057103, 2023).
Hyperglycemia (17 papers, 2013 to 2026). An increased concentration of glucose in the blood. "We demonstrated that hyperglycemia-induced upregulation of endothelial ADAM17 contributed to numerous key responses linked to DR pathogenesis, including oxidative stress, inflammation, and vascular barrier breakdown." (PMID 32024241, 2020). "Our data indicate a novel mechanism whereby hyperglycemia deteriorates podocyte function via ADAM17 activation." (PMID 39859443, 2025). "While hyperglycaemia induced an increase in Ccl5 gene expression, Adam17 deletion in endothelial cells attenuates Ccl5 upregulation in diabetic mice." (PMID 34073747, 2021). "The mechanism by which ADAM17 regulates Nox4 oxidase expression in hyperglycemia is still under investigation and remains to be determined." (PMID 32024241, 2020). "Inactivation of endothelial ADAM17 markedly decreased these effects of hyperglycemia suggesting that ADAM17 activity contributes to hyperglycemia-induced oxidative stress." (PMID 32024241, 2020). "The observed reduction of oxidative stress in mice with inactive endothelium-derived ADAM17 indicates that hyperglycemia-induced ADAM17 activity contributes to increased ROS generation in the diabetic retina." (PMID 32024241, 2020). "Similar to human postmortem tissues, in mouse retinas, hyperglycemia induced a significant increase in the expression levels of ADAM17 (p < 0.01 compared to control age-matched normoglycemic mice)." (PMID 32024241, 2020). "Hyperglycemia, typical in T2D, induces a transcriptional upregulation of ADAM17, and increased ADAM17 protein expression is indeed found in both diabetic patients and in diabetic animal models." (PMID 32930095, 2020). "To test the role of TIMP3 and ADAM17 in DKD we treated C57Bl6 WT mice with streptozocin (STZ) to induce hyperglycaemia." (PMID 23401241, 2013). "This suggests that ADAM17 may be involved in the deterioration of podocyte function by participating in the oxidative stress effects induced by hyperglycemia." (PMID 39859443, 2025). "Also, ACE2 receptors have been reported to act as a compensatory mechanism against hyperglycemia induced-RAS activation since hyperglycemia activates ADAM-17 and ACE2 renal shedding that are common in patients with T2DM and IR." (PMID 34124187, 2021). "Interestingly, this study showed that ADAM17 upregulation in conditions of hyperglycemia might be self-augmented via an EGFR/ADAM17 signaling loop and further implicated ADAM17 as a target in treating diabetic kidney disease." (PMID 39234105, 2024). "In addition, ADAM17 mediates hyperglycemia-induced matrix production in mesangial cells." (PMID 39234105, 2024). "Also, ADAM-17 activation by SARS-CoV-2 leads to hyperglycemia." (PMID 34124187, 2021). "Rosiglitazone treatment of db/db mice normalized hyperglycemia, attenuated renal injury and decreased urinary ACE2 and renal ADAM17 protein expression." (PMID 23646149, 2013). "We anticipate that ADAM17 expression and activity may be reduced with SGLT2 inhibition which may decrease both sympathetic nervous system hyperactivation and hyperglycaemia." (PMID 33904577, 2021). "Therefore, more studies focused on ADAM17; SGLT2 or chronic inflammation interaction should be performed in more detail in the context of hyperglycemia." (PMID 34884897, 2021). "Furthermore, insulin treatment of Akita diabetic mice normalized hyperglycemia and attenuated urinary ACE2 shedding, albuminuria, and renal ADAM17 expression." (PMID 32026607, 2020).
pancreatic cancer (17 papers, 2009 to 2023). "Progression of pancreatic cancer is indeed associated with increased expression of ADAM17, and ADAM17 expression on PDAC cells was shown to be induced by deoxycholic acid, resulting in enhanced release of the EGFR ligands AR and transforming growth factor (TGF) α." (PMID 32698506, 2020). "ADAM17‐mediated shedding of EGFR family ligands has been linked to oncogenic KRAS‐induced pancreatic cancer, suggesting that other ADAM17 substrates may also contribute to mutant KRAS‐driven LAC." (PMID 30833304, 2019). "Studies have shown also the overexpression of ADAM17 in the tumor tissue of esophageal cancer, as well as the participation of this protein in the pathogenesis of pancreatic cancer." (PMID 36286024, 2022). "An extracellular fragment of DSG2 can be shed from the cell surface via MMP9 and ADAM17 and has been documented to be elevated in the serum of patients with pancreatic cancer." (PMID 34245117, 2022). "The meta-survival analysis on pancreatic cancer datasets only showed significance in ADAM17 (HR 1.21; p 0.08)." (PMID 33796097, 2021). "An ADAM17/CD3 bispecific T-cell enganger (BiTE) antibody was able to induce the T-cell mediated lysis of pancreatic cancer cells in vitro." (PMID 32698506, 2020). "This aberrant expression of ADAM17 in pancreatic cancer compared with normal pancreatic tissue was highly significant (P<0.0001)." (PMID 19603023, 2009). "For pancreatic cancer, staining intensities of ADAM17 were scored as intensity 0: 27 cases, intensity 1: 16 cases, intensity 2: 40 cases and intensity 3: 14 cases." (PMID 19603023, 2009). "This study is the first to evaluate ADAM17 as potential prognostic marker in a large number of clinical specimens in pancreatic cancer." (PMID 19603023, 2009). "In analogy to ALCAM expression, we evaluated immunhistochemical staining of ADAM17 expression in pancreatic cancer." (PMID 19603023, 2009). "It has also become clear that ADAM17 is important in cancers mediated by mutations in KRAS, which are the most frequent oncogenic mutations in human cancers, particularly in lung, colorectal and pancreatic tumours." (PMID 35971826, 2022). "However, despite the undoubtfully important role of ADAM17 in tumour disease, our results cannot prove ADAM17 to be a prognostic marker in pancreatic cancer." (PMID 19603023, 2009). "Thus, to answer to what extent the proteolytic sheddase of ALCAM by ADAM17 is a relevant step for tumour progression in pancreatic cancer, further experimental studies are required." (PMID 19603023, 2009). "We could show that ADAM17 is significantly overexpressed in pancreatic cancer compared with normal pancreatic tissue." (PMID 19603023, 2009). "Similarly, inhibition of ADAM17 with an inhibitory antibody likewise suppressed motility in human pancreatic cancer cells in vitro and also significantly delayed tumorigenesis in a murine model, and ADAM17 silencing significantly suppressed hypoxia-induced migration of keratinocytes." (PMID 36293469, 2022). "Taken together, our data identified CUX1 as an important enhancer of KRAS-induced tumor development in pancreatic cancer, acting synergistically with oncogenic KRAS by inducing several upstream and downstream effectors such as ADAM17 and MOS." (PMID 34070180, 2021). "Two components of the Notch signaling pathway, ADAM17 and EP300, were confirmed as miR-148a targets in MiaPaca-2 pancreatic cancer cells overexpressing miR-148a." (PMID 29464088, 2018). "In this study, paraffin-embedded samples of 97 patients with pancreatic cancer undergoing potentially curative resection were immunostained against ALCAM, ADAM17 and CK19." (PMID 19603023, 2009). "To obtain some deeper insight in the last mentioned question, we examined a potential co-expression of ADAM17 and ALCAM in pancreatic cancer." (PMID 19603023, 2009).
pancreatic cancer (continued). "In support of this notion, oncogenic KRAS can modulate ADAM17‐induced shedding of EGFR family ligands during colorectal and pancreatic cancers, and genetic targeting of ADAM17 in mouse models for these cancers suppresses tumorigenesis by abrogating EGFR family ligand production." (PMID 30833304, 2019). "In this study we have confirmed the involvement of miR-148a-ADAM17, miR-148a-EP300, miR-21-PDCD4 and miR-21-BTG2 interactions in the pancreatic cancer cell with the help of genetically modified pancreatic cancer cellular models (stable overexpression or CRISPR/Cas9 knock-out, respectively)." (PMID 29464088, 2018). "We measured the expression of key members of the Notch Signaling Pathway (NUMB, DTX4, DTX3L, PSEN1, APH1A, ADAM17 and EP300) in the MiaPaCa-2-miR-148a by qRT-PCR, and compared it with the basal levels of the control pancreatic cancer cell line MiaPaCa-2, expressing very low levels of miR-148a." (PMID 29464088, 2018). "Thus, we intended to assess a co-expression between ADAM17/TACE and ALCAM in pancreatic cancer and to evaluate a potential co-function." (PMID 19603023, 2009). "Overexpression of ADAM17 in pancreatic cancer, however, failed to be a significant prognostic marker and was not coexpressed with ALCAM." (PMID 19603023, 2009). "However, direct experimental evidence for ADAM17 in an early inflammatory stage of pancreatic cancer is still lacking." (PMID 32698506, 2020). "In summary, the therapeutic targeting of ADAM17 represents an attractive strategy to tackle LAC and other conditions of the lung (e.g., asthma, emphysema), and for that matter, other cancers (e.g., CRC and pancreatic cancer) with aberrant ADAM17 activity and/or expression." (PMID 31438559, 2019). "A total of 71 pancreatic cancer samples were positive for ADAM17 and 26 samples were negative." (PMID 19603023, 2009). "However, knockdown of ADAM17 or treatment with anti-ADAM17 antibody MEDI3622 resulted in regression of pancreatic tumors, accompanied by down-regulated EGFR/STAT3 signaling, increased cytotoxic T cells, and decreased granulocyte-like medullary inhibitory cells in mouse models of pancreatic cancer." (PMID 36466812, 2022). "Although oncogenic KRAS has long been considered to be constitutively active, and thus independent of upstream signals, a requirement for ADAM17 and ERBB1/EGFR in KRAS-induced pancreatic cancer has challenged this idea." (PMID 35971826, 2022). "However, despite its important role in tumour invasion and progression in pancreatic cancer and other types of tumours, immunohistochemical expression of ADAM17 correlates significantly neither with clinical and pathological data nor with ALCAM expression in pancreatic cancer." (PMID 19603023, 2009).